CXCL1 (C-X-C motif chemokine ligand 1)
Diseases named in the same sentence as CXCL1 in open-access papers (continued):
Sharing a sentence is not in itself a finding about the gene and the disease.
breast carcinoma (continued). "Here, we targeted CXCR2 for intervention in mice with mammary tumors, disrupting signals from its cognate ligands, CXCL1 and CXCL3." (PMID 33123173, 2020). "Overall, our study uncovers the immunomodulatory mechanism of XPS in treating breast cancer and highlights TAMs/CXCL1 as a potential molecular target for breast CSCs elimination." (PMID 31803057, 2019). "Mechanism investigations furthered identified the NF-κB/SOX4 signaling as the major target of TAMs/CXCL1 in promoting breast cancer metastasis." (PMID 31803057, 2019). "Taken together, this study not only uncovers the immunomodulatory mechanism of XPS in treating breast cancer but also sheds novel insights into TAMs/CXCL1 as a potential molecular target for breast CSCs elimination." (PMID 31803057, 2019). "The chemokine ligands CXCL-1 and -2 were also shown to promote breast cancer metastasis through myeloid cell recruitment and blocking CXCL-1 and -2 signaling improves chemotherapy efficacy in experimental models." (PMID 30967156, 2019). "This study not only uncovers the immunomodulatory mechanism of XPS in treating breast cancer but also provides novel insights into TAMs/CXCL1 as a potential molecular target for breast CSCs elimination." (PMID 31803057, 2019). "CXCL1 is a chemotactic chemokine and is expressed and secreted from breast cancer stromal cells and has been correlated with poor patient prognosis, high tumor growth and metastasis." (PMID 31341222, 2019). "Meanwhile, consistent with our in vitro findings, XPS administration strongly attenuated the expression of CXCL1 in mammary tumor tissue in vivo." (PMID 31803057, 2019). "More importantly, CXCL1 overexpression in TAMs partly reversed the inhibitory effect of XPS on mammary tumor growth and breast CSCs population." (PMID 31803057, 2019). "CXCL1 is upregulated in various tumors, such as breast cancer, ovarian cancer, prostate cancer, gastric cancer and bladder cancer." (PMID 29662619, 2018). "Bioinformatic analysis and clinical investigation finally suggested that high CXCL1 expression is significantly correlated with breast cancer lymph node metastasis, poor overall survival and basal-like subtype." (PMID 30158589, 2018). "Stromal fibroblasts secrete chemokines, such as Cxcl1, which promote angiogenesis, growth, invasion and metastasis in breast cancer as well as reduced survival in colorectal, bladder and prostate cancers." (PMID 29487713, 2018). "We used MDA-MB-231 and MCF-7 cells to determine if CXCL1 had similar effects on human breast cancer and found that CXCL1 promoted cancer cell migration and invasiveness." (PMID 30158589, 2018). "Although CXCL-1 is expressed by only very few breast cancers, it is present in the lung metastasis signature." (PMID 29890744, 2018). "Compared with other breast cancer subtypes, basal-like subtypes had the highest mean CXCL1 expression according to the TCGA databases." (PMID 30158589, 2018). "Breast cancer cell-secreted CXCL1 recruits CD11b+Gr1+ myeloid cells into the tumor, thereby supporting cancer survival and metastasis by activating calprotectin expression." (PMID 30158589, 2018). "Breast cancer studies by Pawitan and Bild demonstrated that CXCL1 expression had a significant increase in the BRCA1 mutant (P = 0.0035) and triple-negative (P = 0.0005) breast cancer patients, respectively." (PMID 30158589, 2018). "The current study was designed to investigate the level and molecular mechanisms of TAM-derived CXCL1 in promoting breast cancer metastasis." (PMID 30158589, 2018). "CXCL1 is reported to be produced in human breast cancer cell line MDA-MB-23 supernatants, where its downregulation is involved in the protein kinase Syk-mediated suppression of cell migration." (PMID 29887999, 2018). "By gene silencing of the NFκB subunit p65, we found that inhibition of CXCL-1 and -2 expression (CXCL-1: chemokine C-X-C motif ligand 1) by Curcumin in breast cancer cells is mediated through NFκB." (PMID 29890744, 2018).
breast carcinoma (continued). "Here, we showed that CXCL facilitated breast cancer lung aggressiveness in vitro and in vivo but had little effect on breast cancer cell proliferation, indicating that CXCL1 can independently enhance breast cancer cell motility." (PMID 30158589, 2018). "In vivo breast cancer xenografts demonstrated that CXCL1 silencing in TAMs results in a significant reduction in breast cancer growth and metastatic burden." (PMID 30158589, 2018). "Meanwhile, breast cancer patients with both high CXCL1 and NF-κB expression had the poorest OS and RFS (P = 0.0342 and P = 0.0350, respectively)." (PMID 30158589, 2018). "We evaluated the association between the expression of IL-1β plus CXCL1 plus CCL2 plus S100A8 plus VEGF plus IL8 and outcomes in several cohorts of breast cancer patients." (PMID 29262555, 2017). "Taken together, our study provides a candidate formula for preventing breast cancer growth and metastasis, and highlights the role of CXCL-1 in mediating the bioactivities of XIAOPI formula." (PMID 29109519, 2017). "MSCs activated by IL-1β secrete other inflammatory cytokines, such as CXCL1, which is implicated through signaling through CXCR2 expressed on breast cancer cells in the dissemination, poor patient prognosis, chemo-resistance, and metastasis." (PMID 29262555, 2017). "Our findings supported by human data show that breast cancer patients with high-levels of IL-1β, CXCL1, CCL2, S100A8, VEGF, and IL-8 would show worse clinical outcomes." (PMID 29262555, 2017). "All these findings demonstrated the critical role of CXCL-1 in mediating the cancer prevention activities of XIAOPI formula and highlighted the significant effects of CXCL-1 in promoting breast cancer metastasis." (PMID 29109519, 2017). "CCL-19 and -24, CXCL-1 and -10, and IL-6 were increased in dense breast tissue only, whereas IL-18BP was increased in breast cancer only." (PMID 29387062, 2017). "IL-8 has been proven to mediate chemoresistance in breast cancer in our previous report, herein we aimed to investigate the possible role of CXCL1 and CCL5 in hAdSCs-induced doxorubicin resistance in TNBC." (PMID 28750689, 2017). "Therapeutic targeting of the CXCL1/CXCR2 circuit in an adjuvant setting circumvents chemotherapy resistance in breast cancer patients." (PMID 29262555, 2017). "Increased CXCL1/2 production both attracts myeloid cells and causes them to increase their production of S100A8/9 proteins, which increase breast cancer cell survival and chemoresistance." (PMID 27515302, 2016). "Among them, IL-6, IL-8 and CXCL1, previously shown to be important for breast cancer CSCs10, 11, 26, were the top three cytokines that seemed to be most abundantly detected and downregulated following IRAK1 knockdown." (PMID 26503059, 2015). "Increased expression of CXCL1 in breast cancer stroma inversely correlated with expression of Transforming Growth Factor-beta (TGF-β) signaling proteins." (PMID 26252654, 2015). "In recent studies, we demonstrated that CXCL1 was overexpressed in breast cancer stroma, and correlated with increased disease recurrence, and decreased overall survival." (PMID 26252654, 2015). "Recently, it was shown that breast cancer cells expressing elevated levels of CXCL1 and CXCL2 induce the recruitment of MDSCs into the primary mammary tumor." (PMID 25882816, 2015). "CXCR2 and its ligand CXCL1 contribute to the resistance of chemotherapy in mammary tumor cells and the knockdown of CXCR2 enhances sensitivity to chemotherapy and inhibits tumor cell metastasis." (PMID 26313265, 2015). "In these studies, we examined for differences in expression of stromal CXCL1 among the different subtypes of breast cancer." (PMID 25344051, 2014). "Our studies introduce new findings that elevated CXCL1 expression in breast cancer stroma inversely correlate with expression of TGF-β signaling components." (PMID 25344051, 2014).
breast carcinoma (continued). "Tumors are notorious for exploiting this mechanism to aid in their growth and metastasis, as demonstrated by increased tumor growth with the paracrine signaling of CXCL1 in breast cancer." (PMID 25255025, 2014). "Overall, these data indicate higher intensity of CXCL1 expression in breast cancer stroma compared to normal breast stroma." (PMID 25344051, 2014). "Treatment of mammary tumors with Doxorubicin resulted in the selection of drug resistant mammary carcinoma cells with elevated CXCL1 expression in cancer cells." (PMID 25344051, 2014). "We analyzed the cohort of patient samples, in which tumor recurrence was measured after 5 years of treatment, and found a significant correlation between increased CXCL1 RNA expression in breast cancer stroma and increased tumor recurrence." (PMID 25344051, 2014). "In summary, these studies indicate a prognostic significance for CXCL1 expression in breast cancer stroma, show that CXCL1 is localized to multiple fibroblast populations, and is negatively regulated by TGF-β signaling." (PMID 25344051, 2014). "Stromal CXCL1 protein expression was analyzed in 54 normal and 83 breast carcinomas by immunohistochemistry staining." (PMID 25344051, 2014). "To determine the significance of CXCL1 expression in breast stroma, we analyzed the protein and RNA levels of CXCL1 in breast cancer stroma." (PMID 25344051, 2014). "Elevated CXCL1 expression in breast cancer stroma correlated with tumor grade, disease recurrence and decreased patient survival." (PMID 25344051, 2014). "It is possible that increased CXCL1 expression would act in concert with increased growth factor expression to enhance invasiveness of breast carcinomas." (PMID 25344051, 2014). "Our studies indicated that patient samples expressed high levels of CXCL1 RNA and protein in breast cancer stroma, correlating with tumor grade." (PMID 25344051, 2014). "The goal of this study was to further characterize the expression patterns of CXCL1 in breast cancer stroma, determine the prognostic significance of stromal CXCL1 expression, and identify factors affecting stromal CXCL1 expression." (PMID 25344051, 2014). "It is also possible that post-transcriptional and post-translational mechanisms contribute to the differences in CXCL1 RNA and protein expression in breast cancer stroma in lower grade tumors." (PMID 25344051, 2014). "Increased CXCL1 protein expression was associated with increased tumor growth and pulmonary metastasis of MDA-MB-231 breast cancer cells grafted in the mammary fat pads of nude mice." (PMID 25344051, 2014). "In PyMT-induced mammary tumorigenesis, deletion of TβRII was associated with a strong increase in secretion of CXCL1 and CXCL5 chemokines from mammary carcinoma cells and significantly correlated with increased tumor progression and metastasis formation." (PMID 25280532, 2014). "Carcinoma associated fibroblasts isolated from MMTV-PyVmT mammary tumors were treated with recombinant TGF-β and analyzed for CXCL1 promoter activity by luciferase assay, and protein secretion by ELISA." (PMID 25344051, 2014). "CXCL1 has been reported to be overexpressed in colon, skin and breast cancers, but only one study to date has reported on the expression pattern of CXCL1 protein in human bladder tumors." (PMID 23815949, 2013). "Curcumin is able to downregulate the expression levels of inflammatory cytokines CXCL1 and -2 in breast cancer implicating NF-κB transcription factor." (PMID 22069551, 2010). "CXCL1 and -2 are expressed at high levels in very few breast cancers but in many primary and metastatic melanomas (see results section)." (PMID 20030852, 2009). "We show that CXCL1 a chemokine that is down regulated in breast cancer cells by Curcumin in an NFκB dependant manner is expressed at variable levels in human melanomas." (PMID 20030852, 2009).
breast carcinoma (continued). "In addition, binding of TAM-derived CXCL1 to SOX4 promoter enhances its promoter activity via the NF-κB pathway, and silencing CXCL1 in TAMs showed a significant reduction in breast cancer progression and metastasis." (PMID 39858015, 2025). "Furthermore, we discovered that the expression of CXCL8 is highly correlated with that of CXCL1 transcripts in breast cancer cell lines." (PMID 40833805, 2025). "In breast cancer, CXCL1 expression is reduced relative to healthy tissue." (PMID 40427171, 2025). "Also, ionizing radiation increases CXCL1 expression in breast cancer cells, glioblastoma multiforme cells, and non-small-cell lung cancer cells, resulting in a decreased susceptibility of tumor cells to ionizing radiation." (PMID 40427171, 2025). "CXCL1 expression was differentially elevated in older breast cancer patients." (PMID 40584290, 2025). "This research not only offers preclinical evidence that supports the use of ADQ to inhibit lung metastasis in breast cancer but also reveals new perspectives on the TAM/CXCL1/NF-κB/FOXP3 signaling pathway as a viable target for Treg modulation and the immunotherapy of breast cancer." (PMID 39090094, 2024). "We found that Groα/CXCL1 (obesity-associated), MIP-1b/CCL4 (obesity- and HTN-associated), TNFα (HTN-associated), and TGFβ1 and β2 (T2D-associated) were also significantly associated with breast cancer independently." (PMID 38541912, 2024). "It was found that TAMs/CXCL1 promoted chemoresistance of breast cancer cells through autophagy activation in vitro, and CXCL1 silence could enhance the chemosensitivity of paclitaxel-resistant breast cancer cells via autophagy inhibition." (PMID 39394189, 2024). "Groα/CXCL1 was identified in this study as obesity-associated chemokines, and it was also associated with breast cancer independent of obesity." (PMID 38541912, 2024). "In this study, we reported that paclitaxel treatment significantly increased the CXCL1 protein cargo in EV‐Apo, which promoted the invasion and chemoresistance of breast cancer cells by polarizing M2 macrophages via transcriptionally upregulating their PD‐L1 expression." (PMID 39051750, 2024). "The results revealed that TAMs secreted higher levels of CXCL1 compared to breast cancer cells." (PMID 39394189, 2024). "Furthermore, a neutralizing antibody against CXCL1 was introduced into the TAM culture system to assess breast cancer chemosensitivity." (PMID 39394189, 2024). "Moreover, univariate COX analysis showed that the factors including tumor stage, N stage, CD163 expression, CXCL1 expression, HMGB1 expression, and IGF1R expression were significantly associated with breast cancer prognosis." (PMID 39394189, 2024). "C-X-C motif chemokine ligand 1 (CXCL1) is the chemokine that TAMs secrete most abundantly, and TAMs/CXCL1 signaling has been demonstrated to aggravate breast cancer progression by enhancing the epithelial-mesenchymal transition and pre-metastatic niche formation." (PMID 39394189, 2024). "Previous studies suggested that CXCL1 could induce autophagy-mediated chemoresistance in breast cancer cells by regulating HMGB1." (PMID 39394189, 2024). "Overall, these data suggested that CXCL1 might induce autophagy by regulating the IGF1/IGF1R signaling in breast cancer." (PMID 39394189, 2024). "The comorbidity-driven inflammation and increasing cytokines, such as TNFα and Groα/CXCL1, might contribute to the early onset of breast cancer in this cohort of AA and LA women." (PMID 38541912, 2024). "Moreover, western blotting analysis revealed an increase in ABCG2 and LC3-II accumulation, as well as a decrease in SQSTM1/p62 expression in breast cancer cells treated with CXCL1 for 24 h." (PMID 39394189, 2024). "In addition, CXCL1 has been found to show higher expression levels in TNBC than other breast cancer subtypes." (PMID 38654356, 2024). "A high expression of Groα/CXCL1 in breast cancer promoted cell invasion via the MAPK pathway." (PMID 38541912, 2024).
breast carcinoma (continued). "Hence, targeting CXCL1/CXCR2 signaling has emerged as a pivotal strategy for improving the prognosis of breast cancer, with potential benefits for patients resistant to chemotherapy through the use of CXCL1/CXCR2 antagonists." (PMID 39394189, 2024). "Nevertheless, the precise mechanism by which TAMs/CXCL1 regulate chemoresistance remains unclear in breast cancer." (PMID 39394189, 2024). "Indeed, the presence of CXCL1 significantly increased breast cancer 4T1 cell migration and invasiveness ability, matrix metalloproteinase-2 (MMP-2) and MMP-9 secretion, as well as the expression of EMT-related proteins in vitro." (PMID 38397187, 2024). "For example, CXCL1 could accelerate the immune escape of breast cancer and non‐small cell lung cancer by recruiting CXCR2+ Tregs to establish immunosuppressive TME." (PMID 39051750, 2024). "High CXCL1 expression correlates with advanced disease and poor prognosis in breast cancer." (PMID 39456897, 2024). "CXCL1 is also important in breast cancer lymph node metastasis." (PMID 37108425, 2023). "Other factors are also responsible for CXCL1 expression in breast cancer." (PMID 37108425, 2023). "CXCL1 seems to be involved in the formation of brain metastasis of breast cancer." (PMID 37108425, 2023). "Additionally, a mutation in KRAS leads to the activation of mitogen-activated protein kinase (MAPK) cascades, which then leads to increased CXCL1 expression in breast cancer cells." (PMID 37108425, 2023). "CXCL1 increases the proliferation of breast cancer cells, as has been shown in experiments on triple-negative MDA-MB-231 breast cancer lines, triple-negative HCC-1937 breast cancer cells, HER2-negative MCF-7 cells, and HER2-positive SKBR3 breast cancer cells (ER−PR−HER2+)." (PMID 37108425, 2023). "Interestingly, TAMs/CXCL1 signal was also proved to enhance breast cancer stemness in the previous study." (PMID 37210553, 2023). "The frequency of CXCL1 amplification increases with the progression of breast cancer." (PMID 37108425, 2023). "CXCL1 expression in breast cancer cells is lineage dependent." (PMID 37108425, 2023). "CXCL1 is also important in the function of breast cancer stem cells." (PMID 37108425, 2023). "CXCL1 has pro-survival and anti-apoptotic effects on breast cancer cells." (PMID 37108425, 2023). "When it comes to subtypes of breast cancer, CXCL1 gene amplification was observed in 1.20% (6/499) of luminal A breast cancer cases, 3.55% (7/197) of luminal B breast cancer cases, 7.69% (6/78) of HER2-positive breast cancer cases, and 1.17% (2/171) of basal breast cancer cases." (PMID 37108425, 2023). "Other proteins also affect CXCL1 expression in breast cancer." (PMID 37108425, 2023). "CXCL1 expression in breast cancer cells is downregulated by TGF-β." (PMID 37108425, 2023). "Among these different CAF subtypes, iCAFs are reported to have a particular effect on chemoresistance in breast cancer patients, probably due to their high secretion of cytokines involved in therapy resistance, such as CXCL1–3, CCL2, CSF3, CXCL10, IL1β and LIF." (PMID 36710348, 2023). "Additionally, in breast cancer with BRCA1 or BRCA2 gene mutations, the amplification percentage of CXCL1 gene is 3.85% (2/52)." (PMID 37108425, 2023). "However, a previous study showed that Th17 cells produced C-X-C motif chemokine ligand 1 (CXCL1) during breast cancer progression, which enhanced cancer cell invasion." (PMID 37275874, 2023). "Taken together, these findings suggest that CXCL1 may be an important target for inhibiting the pre-metastatic lung microenvironment to suppress lung metastasis in breast cancer." (PMID 36607556, 2023). "Other CXCR2 ligands may play a more important role in breast cancer than CXCL1, for example, CXCL5/epithelial-cell-derived neutrophil activating factor 78 (ENA78) and CXCL8/interleukin-8 (IL-8), whose expression is increased in breast tumors." (PMID 37108425, 2023).